TCF7L2 (transcription factor 7 like 2)
Diseases named in the same sentence as TCF7L2 in open-access papers (continued):
Sharing a sentence is not in itself a finding about the gene and the disease.
Obesity (continued). "Our study indicates that the effects of TCF7L2 rs7901695 genetic variants on glucose homeostasis and obesity-related parameters may depend on daily macronutrient intake." (PMID 34200102, 2021). "Besides FTO polymorphisms, KCNJ11 rs5219, KCNQ1 rs2237892, and TCF7L2 rs7901695 variations have previously been linked to obesity in patients with T2DM." (PMID 34442333, 2021). "The results were further supported by the fact that obesity surgery-induced weight loss could regulate the alternative splicing of TCF7L2 in subcutaneous fat." (PMID 29713286, 2018). "Also, two Single Nucleotides polymorphism (SNPs) are associated with T2DM risk: transcription factor 7-like 2 (TCF7L2) and fat mass and obesity-associated (FTO) gene on chromosome 16." (PMID 27894098, 2017). "More precisely, several GWASs with obesity have confirmed that the statistically associated loci, transcription factor 7-like 2 (TCF7L2) and fat mass and obesity-associated protein (FTO), may provide novel insight into the pathophysiology of obesity." (PMID 28508896, 2017). "Furthermore, we estimated the influence of obesity status on T2D incidence over the 5.7-year median follow-up period in this population in the whole sample and depending on the TCF7L2-rs7903146 polymorphism." (PMID 27929407, 2016). "Previously published results of this project have found a relationship between the rs12255372 variant of the TCF7L2 gene and obesity; however, this gene is associated with diseases such as T2D in adults, but it appears to protect against the development of obesity in children." (PMID 25885348, 2015). "Additionally, a study revealed that the rs12255372 variant of TCF7L2 was protective for obesity in Mexican children." (PMID 26608632, 2015). "ENPP1, ADIPOQ, PPARG and TCF7L2 single nucleotide polymorphisms (SNPs) have previously been associated with T2D and have shown variable significance amongst different classes of obesity." (PMID 18498634, 2008). "This large case-control study further supports the hypothesis that the T2D risk contribution of ENPP1, ADIPOQ, PPARG and TCF7L2 SNPs may be modulated by obesity status." (PMID 18498634, 2008). "Our findings suggest that associations of the common TCF7L2 SNP with glucose homeostasis and obesity-related parameters may be dependent on daily macronutrient intake, which warrants further investigations in a larger population, as well as interventional studies." (PMID 34200102, 2021). "Therefore, the aims of this nutrigenetics study were to evaluate the potential interaction between three candidate SNPs, rs1558902 and rs9939609 in the FTO gene and the rs7903146 variant of the TCF7L2 gene, and macronutrient intake with regard to obesity, body fat and muscle composition." (PMID 30764585, 2019). "In our Thai population, we found that TCF7L2 rs61875103, a well-known beta-cell function variant, was strongly associated with the MOD cluster, suggesting that even among individuals with obesity-driven T2D, beta-cell dysfunction contributes substantially." (PMID 41422334, 2025). "GMDR analysis revealed that the rs7901695 site of the ABCG1 gene and the cg06500161 site of the TCF7L2 gene interacted with hypertension, dyslipidemia, abdominal obesity, and obesity, as well as with drinking, smoking, and exercise." (PMID 40225014, 2025). "In obesity, the protein level of TCF7L2 is reduced in whole adipose tissue but increased in adipocyte progenitor." (PMID 38396716, 2024). "Humans with impaired glucose tolerance and adipocyte insulin resistance, humans with obesity, and mice with high-fat diet-induced obesity showed low TCF7L2 levels." (PMID 38396716, 2024). "In the present study, we set out to characterize the molecular function of TCF7L2 in the CNS with the goal of understanding its possible role in the comorbidity of BD and obesity." (PMID 34535768, 2021).
Obesity (continued). "Their variants affect the obesity risk by modulating the binding affinity of obesity-related transcription factors, such as STAT3, CEBPB, TCF7L2, FTO, and GATA2, and changing the phosphorylation of proteins, such as BDNF with the rs6265 risk allele." (PMID 34836030, 2021). "The TCF7L2 rs7903146 T allele increased T2DM risk in the normal weight group and interacted with sex, age and BMI, while the C allele increased obesity risk." (PMID 33996288, 2021). "In support of this notion, expression of Tcf7l2 in mice and TCF7L2 in humans negatively correlates with BMI, which is in line with our observation that knockdown of pop-1 promotes obesity in C. elegans." (PMID 34492009, 2021). "In the present study, we functionally characterized TCF7L2 in astrocytes, CNS cells that highly express TCF7L2, in an attempt to understand its possible role in the comorbidity of BD and obesity." (PMID 34535768, 2021). "Nutrigenetic studies within a cohort of MD consumers showed a close relation between the allelic variants rs7903146 C>T in the Transcription Factor 7-Like 2 (TCF7L2) gene, obesity, and T2D." (PMID 32545252, 2020). "GLP-1 receptor and TCF7L2 mRNA levels in the media were significantly lower in obesity group compared to non-obesity group (p < 0.01 and p = 0.02, respectively) which was also consistent with the immunostaining data." (PMID 30006590, 2018). "GLP-1 receptor and TCF7L2 mRNA levels in the intima were significantly lower in obesity group compared with that in non-obesity group (p < 0.01 and p = 0.03, respectively), which was consistent with the immunostaining results." (PMID 30006590, 2018). "Taken together, vascular GLP-1 receptor and TCF7L2 expression was significantly down-regulated in human subjects with obesity." (PMID 30006590, 2018). "In conclusion, we provide strong evidence supporting the need for considering obesity when analyzing the TCF7L2 effects and propose the use of obesity-specific GRS for T2D." (PMID 27929407, 2016). "In this investigation, we carried out genetic association study of the SNPs in PPAR-γ2 and TCF7L2 with T2DM susceptibility and its interaction with the obesity status for the first time in the Emirati population." (PMID 26273662, 2015). "For example, the associations between TCF7L2, TSPAN8/LGR5, FTO and MetS T2D were attenuated when adjusted for BMI, suggesting the role of obesity." (PMID 26599349, 2015). "Our case-control study is the first of its kind in Emiratis which establishes TCF7L2 rs10885409 C allele as a T2DM risk factor in Emiratis and this association is modulated by obesity status." (PMID 26273662, 2015). "In addition, the same previously genotyped cohort was also investigated for its possible link to obesity, revealing only five allelic variants [FTO and TCF7L2 genes] out of 37 were associated with obesity in the Saudi Arabian population." (PMID 36980809, 2023). "However, some studies demonstrate involvement of TCF7L2 in body weight regulation and the development of obesity and T2D due to impairment of β-cell function and then insulin secretion." (PMID 35292917, 2022). "Genome-wide association studies (GWAS) identified several genes such as the glucokinase (GCK), the glucokinase regulator (GCKR), the transcription factor 7-like 2 (TCF7L2), the hepatocyte nuclear factor-1A (HNF1A), and fat mass and obesity-associated (FTO) gene playing a role in developing T2DM." (PMID 35486295, 2022). "The aim of our study was to evaluate whether daily macronutrient intake may alter the impact of the TCF7L2 gene on glucose homeostasis and obesity-related parameters." (PMID 34200102, 2021). "In addition, physical activity alter DNA methylation of T2DM gene candidates such as FTO (fat mass and obesity-associated protein; associated with energy intake) and TCF7L2 (transcription factor 7-like 2; blood glucose homeostasis) in adipose tissue." (PMID 34140928, 2021).
Obesity (continued). "However, more studies are required to understand further the mechanisms interconnecting the TCF7L2 rs7903146 variant, T2DM and obesity." (PMID 33996288, 2021). "Thus, the primary objectives of this study were to evaluate the TCF7L2 rs7903146 association with T2DM according to BMI status and to determine if this variant is related to obesity and BMI variation in a cohort of elderly Brazilians." (PMID 33996288, 2021). "The aim of our cross-sectional population-based study was to analyze whether daily macronutrient intake may influence the effects of the TCF7L2 rs7901695 genotype on glucose homeostasis and obesity-related parameters." (PMID 34200102, 2021). "We evaluated the TCF7L2 rs7903146 association with T2DM and obesity." (PMID 33996288, 2021). "We notably found that carbohydrates may have an impact mostly on the obesity-related parameters, dependently on the carried genotype of TCF7L2 rs7901695." (PMID 34200102, 2021). "Besides the FTO, Melanocortin 4 Receptor (MC4R) and Transcription Factor 7-Like 2 (TCF7L2) genes are the two commonly studied candidate genes for obesity and T2D." (PMID 32397403, 2020). "The specific mechanism between TCF7L2 and obesity development remains a mystery." (PMID 30065654, 2018). "TCF7L2 is one of the genes that have been identified as possible determinants of obesity." (PMID 28420445, 2017). "Absence of association with obesity was also demonstrated for other polymorphisms of TCF7L2 including rs10885406 in US populations." (PMID 28420445, 2017). "In a study among Caucasians, the effect of TCF7L2 on T2DM was modulated by obesity." (PMID 28420445, 2017). "Indeed, it was shown in a Caucasian population that the effect of TCF7L2 on T2DM is modulated by obesity." (PMID 28420445, 2017). "Moreover, this heterogeneity of the TCF7L2-rs7903146 effects on T2D can be extended to other T2D SNPs and we have created for the first time the concept of obesity-specific GRS." (PMID 27929407, 2016). "We analyzed the interaction between the TCF7L2-rs7903146 polymorphism and obesity status in determining the incidence of T2D in non-diabetic subjects (n = 3607) over the extended follow-up period (with median 5.7 years)." (PMID 27929407, 2016). "Although TCF7L2 was not identified as a risk factor for obesity in a study involving European populations, its effect on the risk for T2DM was modulated by obesity." (PMID 26608632, 2015). "This study on Cameroonian subjects replicates the absence of association between the TCF7L2 rs12255372 variant and obesity as observed in European and American populations." (PMID 26608632, 2015). "Initial approaches in African Americans have examined candidate variants or genes with the largest effects and/or biologic plausibility, including FTO for obesity and TCF7L2 for T2D which has then ultimately led on to fully executed GWAS approaches in this ethnicity." (PMID 23577239, 2013). "The TCF7L2 obesity association was stochastically independent of the FTO association if assessed in a multiple regression analysis." (PMID 20092643, 2010). "Obese carriers of the TCF7L2‐rs7903146 TT‐genotype have 2.62‐times higher odds of T2D compared to those with other genotypes, and this relationship appears even stronger after adjusting for obesity‐onset age, male gender, dyslipidemia, and lower serum total adiponectin." (PMID 34612510, 2022). "The protective role of Tcf7l2 in glucose homeostasis may suggest a protective role in obesity too." (PMID 34492009, 2021). "Therefore, future study of the role of TCF7L2 in human obesity is warranted." (PMID 34492009, 2021). "Likewise, other studies have found some common polymorphisms such as the transcription factor TCF7L2, which may be important in precision medicine as well as a potential predictive biomarker in patients with T2DM and obesity." (PMID 32917030, 2020). "The absence of association between TCF7L2 rs7903146 and obesity in our population may be explained by the small size of our study population." (PMID 28420445, 2017).
Obesity (continued). "The rs7903146 (C/T) polymorphism of the TCF7L2 gene might not be associated with obesity in the Cameroonian population." (PMID 28420445, 2017). "Nevertheless, this potential heterogeneity by obesity has not been widely reflected in the analytical approaches of subsequent investigations, and most of them have not formally tested the interaction between the TCF7L2-rs7903146 polymorphism and obesity status in determining T2D risk." (PMID 27929407, 2016). "Furthermore, for some of the candidate genes for T2D, T2D related traits and obesity identified by GWAS, we found both differential mRNA expression and changes in DNA methylation in islets exposed to palmitate, for example, TCF7L2 and GLIS3 show decreased expression and increased DNA methylation." (PMID 24953961, 2014). "Acute depletion of TCF7L2 in the liver resulted in higher blood glucose levels that were associated with increased glucose intolerance and up-regulation of gluconeogenic genes, while ectopic expression of nuclear TCF7L2 in C57BL/6 mice with diet-induced obesity (DIO) improved glucose tolerance." (PMID 23028378, 2012). "The lack of association of TCF7L2 variation with birth weight was also supported by the analysis of another cohort of French children ascertained by further development of early onset obesity." (PMID 17593304, 2007). "Our selected gene variant represents only a fraction of the studied gene’s potential variation and the mechanisms involving TCF7L2, T2DM and obesity." (PMID 33996288, 2021). "Notably, of 104 GO functional categories, two GO terms “glucose homeostasis” and “response to glucose” were also enriched by T2D GWAS genes (such as TCF7L2 and FTO), indicating that obesity associated genes might confer T2D risk through its primary effect on adiposity." (PMID 29966015, 2018). "Generalized multifactor dimensionality reduction (GMDR) showed that the rs7901695 locus of the TCF7L2 gene and the cg06500161 locus of the ABCG1 gene had interaction with hypertension, dyslipidemia, abdominal obesity, and obesity and also had interaction with drinking, smoking, and exercise." (PMID 40225014, 2025). "GLP-1 receptor expression in intima and media was lower in obesity group compared to non-obesity group which was correlated with the alteration of TCF7L2 expression." (PMID 30006590, 2018). "Both TCF7L2 and KCNQ1 have been shown to play essential roles in beta cell survival and function, and they have been suggested to be involved in the modulation of insulin sensitivity and obesity." (PMID 23990951, 2013). "It was previously demonstrated that the genetic effects of variants associated with either insulin secretion (like for GCK, KCNJ11 or TCF7L2) or insulin action (for ENPP1, ADIPOQ or PPARG) may be modulated by the obesity status or adiposity." (PMID 19368707, 2009). "Exploration of associations between genotypes and metabolic/obesity related variables in patients with PCOS revealed some evidence for an association of variants in FTO and TCF7L2, whereas no indication of association was observable for SNPs in INSIG2 and MC4R." (PMID 20092643, 2010). "After we launched this project, other SNPs were identified in obesity or T2D GWAS, including MCR4, TCF7L2 and EXT2, but were not included in our study." (PMID 27990199, 2009).
colorectal cancer (91 papers, 2009 to 2025). A primary or metastatic malignant neoplasm that affects the colon or rectum. "Despite the mutual dependence of β-CATENIN and TCF7L2 in healthy IECs and for tumor initiation, high proportions of colorectal cancer genomes carry inactivating mutations in the TCF7L2 gene." (PMID 36609428, 2023). "TCF7L2 exhibits polymorphisms which results in loss of function and can promote metastatic phenotypes in colorectal cancer." (PMID 34367349, 2021). "Yet, TCF7L2 belongs to the most frequently mutated genes in colorectal cancer (CRC), and tumor-suppressive functions of TCF7L2 were proposed." (PMID 32203164, 2020). "The Wnt pathway is a major driver of colorectal carcinogenesis and the TCF7L2 gene is frequently mutated in colorectal cancer." (PMID 32705315, 2020). "TCF7L2 mutations have been frequently observed in colorectal cancers as various types of genomic aberrations including mutations, gene fusions, and chromosomal deletions." (PMID 32023847, 2020). "Another article reported that a TCF7L2 missense variant rs138649767 associates with colorectal cancer risk by interacting with a GWAS-identified regulatory variant rs698326 in the MYC enhancer." (PMID 30627228, 2018). "The rs6983267 variant in a transcriptional enhancer on chromosome 8q24 is associated with colorectal cancer pathogenesis because it binds differentially to transcription factor 7-like 2 (TCF7L2) and cMyc." (PMID 29299175, 2017). "TCFs—particularly TCF7 and TCF7L2—have been implicated across different tumor types, with a particularly strong link to colorectal cancer." (PMID 27527215, 2016). "T-cell Factor/Lymphoid Enhancer Factor (TCF/LEF) transcription factors are major regulators of Wnt targets, and the products of the TCF7 and TCF7L2 genes have both been implicated in the progression of colorectal cancer in animal models and humans." (PMID 27527215, 2016). "We have previously reported whole genome sequence analysis of nine colorectal carcinoma/normal pairs,leading to the identification of activating translocations of TCF7L2 and of the association of Fusobacterium nucleatum with colorectal carcinomas." (PMID 24894453, 2014). "While genetic alterations of Wnt pathway components, such as APC, β-catenin, axin and TCF7L2 are implicated in colorectal cancers, melanoma, gastric and hepatocellular carcinomas, they are rarely associated with breast cancer." (PMID 23516639, 2013). "For example, functional deficiency of TCF7L2 promotes metastasis of colorectal cancer." (PMID 39060928, 2024). "Moreover, loss of the nuclear Wnt pathway effector TCF7L2 promoted migration and invasion of human colorectal cancer cells." (PMID 34976185, 2022). "Interestingly, nine have been implicated in GI disorders; for example, Nfil3 deficiency has been associated with colitis, NFIL3 is a susceptibility gene for inflammatory bowel disease, and TCF7L2 has been implicated in colorectal cancer." (PMID 34165249, 2021). "Besides, subtypes c1 had the characteristic of high frequent copy loss of TCF7L2 which can promote migration and invasion of human colorectal cancer cells reported by the latest study." (PMID 32680494, 2020). "Rare point mutations within TCF7L2 are also found in colorectal cancers." (PMID 19895682, 2009). "To date, many studies have been published investigating the association between TCF7L2 rs7903146 or rs12255372 (it is in high linkage disequilibrium with rs7903146) and several types of cancer, including breast cancer, prostate cancer, colorectal cancer, colon cancer, lung cancer and ovarian cancer." (PMID 23951231, 2013). "The three other genes of the pathway that are frequently mutated in colorectal cancer samples, RNF43, CTNNB1, and TCF7L2, were also frequently mutated in colorectal cancer cell lines, although less frequently than APC." (PMID 40061138, 2025).